IL6 (interleukin 6)
Diseases named in the same sentence as IL6 in open-access papers (continued):
Sharing a sentence is not in itself a finding about the gene and the disease.
Obesity (continued). "Employing functional candidate analysis, we recently identified association of common variants of IL6, LEPR, and PBEF1 with increased susceptibility to obesity and measures of adiposity in Indian children." (PMID 22496743, 2012). "Obesity in both human and animal models has been associated with increased inflammatory markers, including TNF-α and IL-6." (PMID 22518191, 2012). "In the setting of obesity, the ability of the adipose tissue to produce antiinflammatory mediators such as adiponectin decreases, whereas proinflammatory cytokines such as IL-6, TNF-α, and acute phase reactants, and other innate immune mediators increase." (PMID 22509382, 2012). "We achieved our aim and identified a down-regulation of IL-6Rα in obesity and an abnormal IL-6 signaling in myocytes from people with type 2 diabetes." (PMID 22761857, 2012). "Taken together, regulation of the IL-6/STAT3/SOCS3 pathway in muscle cells seems to change with obesity, possibly due to alterations in circulating cytokine levels and composition." (PMID 22761857, 2012). "It is possible, only at this level of obesity (or above), for sufficient inflammatory cytokine, such as IL-6 is available in maternal blood, to have any meaningful effect on fetal neurodevelopment." (PMID 22188548, 2012). "It has been documented that the expression of IL-6 in adipose tissue and its serum concentrations positively correlate with obesity, insulin resistance, and T2D, even with insulin resistance in cancer patients." (PMID 22701472, 2012). "The concentration of IL-6 was higher in all groups with RА than in controls; however, in the group with obesity it was higher than in the group with normal BMI, and in the group with normal BMI it was higher than in underweight patients." (PMID 22911528, 2012). "IL-6 secreted by immune cells, adipocytes and endothelial cells plays a well known role in the chronic low-grade inflammation characteristic of obesity, diabetes and cardiovascular disease, as well as the acute immunological crises of infection and sepsis." (PMID 22347395, 2012). "Inflammatory state of obesity is characterized by insulin resistance, increased serum concentrations of C-reactive protein, IL-6, IL-8, TNF-α, and so forth." (PMID 23091306, 2012). "One candidate protein involved in skeletal muscle metabolism, and also regulated during obesity and diabetes is interleukin (IL)-6." (PMID 22761857, 2012). "Both mammary gland involution and obesity have been demonstrated to result in the elevation of a variety of inflammatory regulators, such as IL-6 and TNF-α, among others." (PMID 22403677, 2012). "In the multivariate analysis muscle myostatin mRNA content was predicted by age and plasma IL-6, when adjusting for insulin resistance, plasma triglycerides and obesity." (PMID 22615949, 2012). "We have identified an abnormal IL-6 signaling in differentiated muscle precursor cells isolated from people with obesity and type 2 diabetes." (PMID 22761857, 2012). "Concentrations of IL-6 are increased in obesity and have been shown to predict the incidence of type 2 diabetes in individuals." (PMID 23028874, 2012). "Adipose tissue is one of the major sources of IL-6, a pro-inflammatory cytokine that is elevated in states of obesity and insulin resistance." (PMID 22848362, 2012). "Recent data have revealed that the plasma concentrations of inflammatory mediators, such as TNF-α, MCP-1 and IL-6, are increased in the insulin resistant states of obesity." (PMID 21589925, 2011). "Interleukin-6 (IL-6) is an inflammatory cytokine which is produced by both macrophages and adipocytes and whose release is increased in obesity." (PMID 21966540, 2011). "IL-6, CRP, and TNF-α are the main inflammatory molecules associated with obesity-related inflammation." (PMID 21599899, 2011). "Resistin expression is stimulated by TNFα and IL-6, both of which are increased in obesity, which offers an explanation for an increased level of resistin in obesity." (PMID 21410966, 2011).
Obesity (continued). "The high levels of NA and IL-6 (and IL-1β) found in obese animals may reflect defective regulation of the negative inflammatory/stress feedback loop in MS - a physiological state that may in turn be either the cause or the consequence of the diabetes associated with obesity." (PMID 21599899, 2011). "For example, in obese Zucker rats, the beneficial effect of exercise training on obesity and diabetes has been linked to anti-inflammatory mechanisms, with improvements in the circulating levels of CRP, adiponectin, IL-6, and TNF-α." (PMID 21599899, 2011). "Obesity reflects ageneralized proinflammatory state with its increased inflammatorymarkers like C reactive protein, IL-6, IL-8, IL-10, PAI-1,TNF-α, and hepatocyte growth factor." (PMID 21991518, 2011). "IL-6 expression in adipose tissue and its circulating levels are positively correlated with obesity, impaired glucose tolerance, and IR." (PMID 22007189, 2011). "The multifunctional cytokine IL-6 is clearly involved in the regulation of metabolism, with confirmation of the link between obesity and inflammation." (PMID 21599899, 2011). "It is estimated that approximately one-third of total circulating IL-6 is produced by adipose tissues, and it is possible that increased secretion of IL-6 under conditions of obesity contributes to metabolic dysfunction." (PMID 21960997, 2011). "It is well known that high-fat diets or obesity result in the activation of NF- kappaB, leading to over-expression of its target genes such as IL-6, iNOS, TNF alpha." (PMID 21999347, 2011). "In obesity, an increase in cytokine IL-6 has been observed at the mRNA and protein levels in white adipose tissue." (PMID 21410966, 2011). "Activation of TLR4 causes the secretion of IL-6 and TNF-α, supporting the role of LPS in triggering the downstream inflammatory processes associated with obesity, such as metabolic disease." (PMID 22115311, 2011). "It is now well established that obesity is characterised by chronic inflammation, with associated increases of CRP, interleukin-6 (IL-6) and plasminogen activator inhibitor." (PMID 21081932, 2011). "In animal models of diet-induced and genetic obesity increased production of IL-1, IL-6, TNF-α and Toll-like receptor (TLR) signaling in adipose tissue has also been reported." (PMID 22115311, 2011). "Results of liver transcriptome analysis along with markers of oxidative capacity (SDH enzyme activity, Il6 expression) in skeletal muscle suggests of multiple tissue metabolic interactions in the obesity resistant Lean line." (PMID 21291556, 2011). "Recent in vivo data in dietary and genetically obese mouse models demonstrated obesity-related liver inflammation and subsequent release of IL-6 and TNFα." (PMID 21081932, 2011). "Obesity and smoking increase the expression of proinflammatory cytokines, including IL-1, IL-6 and TNFα." (PMID 20646281, 2010). "Adipose tissue macrophages (ATMs) are proved to be predominantly responsible for the elevated production of TNF-α and IL-6 during obesity." (PMID 21403905, 2010). "Growing evidence shows elevation of plasma IL-6 and TNF-α concentrations in depressed and diabetic patients and IL-6 represents the higher association with obesity and insulin resistance." (PMID 20490354, 2010). "Obesity, a major risk factor for diabetes, is a state of chronic inflammation and is associated with elevated levels of CRP, IL-6 and plasminogen activator inhibitor-1 (PAI-1)." (PMID 20976133, 2010). "Mast cells contribute to production of IL-6, interferon-γ, and metabolic complications of obesity, including insulin resistance and fatty liver." (PMID 20701600, 2010). "The proinflammatory cytokines TNF-α and IL-6 play important roles in obesity and the evolution of the disease." (PMID 20300479, 2010). "An important link between obesity and MM is elevated expression of IL-6 in adipose tissue and bone marrow, which also leads to elevations in circulating IL-6." (PMID 20204067, 2010).
Obesity (continued). "IL6 provides an important link between obesity, aging, chronic inflammation and cancer, and a wealth of genetic models now permits detailed dissection of the contribution of individual signaling components within specific cell types." (PMID 20478049, 2010). "Several studies suggest that TNF-α and IL-6 are both involved in obesity-related insulin resistance and that TNF-α is one of the most important mediators of inflammation." (PMID 20825686, 2010). "In obesity, inflammatory cytokines (IL-1β, TNFα, and IL-6) and adiponectin released from AT reach the liver through the portal vein and can directly interfere with liver functions." (PMID 20508742, 2010). "Here, we have obtained clear evidence that endurance exercise and CR led to potent suppression of pro-inflammatory cytokines including osteopontin, TNF-α, MCP-1 and IL-6, all of which have been shown to be elevated in the state of obesity and type 2 diabetes." (PMID 20633301, 2010). "As in aging, fat tissue adipogenic transcription factor expression is decreased in obesity, and inflammatory mediators, including TNFα and IL-6, are increased." (PMID 20701600, 2010). "The pro-inflammation cytokines such as TNF-α and IL-6 have been demonstrated to mediated insulin resistance as a result of obesity in many rodent obesity models." (PMID 20107539, 2009). "Increased IL-6 levels in obesity can directly interfere with the insulin signaling and contribute to insulin resistance." (PMID 19545451, 2009). "Tumor necrosis alpha (TNF-α) and interleukin 6 (IL-6), pro-inflammatory cytokines produced mainly by adipocytes and macrophages but also by muscle cells, are up-regulated in obesity." (PMID 19333447, 2009). "Yet based on the current data, it can be assumed that IL-6 exerts different effects according to the physiological situation, i.e. in response to exercise or during low-grade inflammation in obesity." (PMID 19333447, 2009). "Since IL6 represents a major inflammatory cytokine that is over expressed in adipocytes in obesity, we first sought the possibility of its induction in response to peptidoglycan." (PMID 19348674, 2009). "Type 2 diabetes and obesity have characteristics of inflammatory conditions with increased blood levels of pro-inflammatory cytokines, such as interleukin (IL)-6, IL-1 and TNF-α, which attenuate insulin receptor signaling." (PMID 19114996, 2008). "The incidence of obesity and its co-morbidities has increased dramatically worldwide, and is characterized by systemic inflammation with an important, central role for IL-6." (PMID 19936194, 2008). "Circulating levels of interleukin-6 (IL-6) are raised in insulin resistant states such as obesity, impaired glucose tolerance (IGT), and type 2 diabetes mellitus (DM)." (PMID 17374166, 2007). "Plasma levels of CRP, TNF-α, and IL-6, which are markers of inflammation, are elevated in obesity, insulin resistance, essential hypertension, type 2 diabetes, and CHD both before and after the onset of these diseases." (PMID 18078524, 2007). "Individuals with diabetes and those with concurrent diabetes, obesity, andhypertension also demonstrated larger associationsbetween PM2.5 and IL-6." (PMID 16835049, 2006). "Persons with diabetes, obesity, and hypertensionalso exhibited positive associations between PM2.5 and IL-6." (PMID 16835049, 2006). "Such pro-inflammatory factors include tumour necrosis factor alpha (TNF-α), interleukin 6 (IL-6) and leptin, which are secreted by adipocytes and are elevated in obesity and insulin resistant states." (PMID 15998471, 2005). "Among these, IL-6 knockout mice develop mature-onset obesity, and treatment of hepatocytes with IL-6 reduces the expression of PCK1, thus implicating IL-6 in the regulation of hepatic glucose output." (PMID 15985155, 2005).
Obesity (continued). "In general, the G2 subgroups with obesity showed higher levels of pro-inflammatory cytokines IL-1β, IL-6, IFN-γ, and TNF-α than the respective G1 subgroups, and also an association of CMI in favor of a pro-inflammatory systemic status, particularly in the older women group." (PMID 41602164, 2026). "Interestingly, endometriosis and obesity share similar pathological markers, including leptin, adiponectin, tumor-necrosis-factor-α, and interleukin-6." (PMID 41798441, 2026). "Additionally, both VEGF and IL-6, right after leptin, showed the highest statistical ability in relation to higher blood pressure values in people with obesity." (PMID 41596212, 2026). "In addition, CRP is easily disturbed by metabolic factors such as obesity and hyperlipidemia, resulting in poor specificity; IL-6 has a short half-life and the blood concentration fluctuates greatly, so it is not easy to grasp the timing of detection." (PMID 41517734, 2026). "Chronic systemic inflammation with persistently elevated IL-6, as seen in metabolic syndrome and obesity, can, over time, lead to diffuse myocardial fibrosis and heart failure with preserved ejection fraction through its profibrotic and prohypertrophic effects." (PMID 41590667, 2026). "The majority of participants harbored risk alleles within the fat mass and obesity-associated gene (FTO) and the interleukin-6 gene (IL-6), together with multiple additional significant variants identified across more than 40 genes implicated in metabolic regulation and nutritional status." (PMID 41683970, 2026). "On the contrary we do find inflammatory cytokines like IL-1β which shows an association with diabetes type 2 but not obesity while IL-6 is more closely associated with obesity than diabetes." (PMID 41710408, 2026). "While IL-6 and ferritin levels might be similar in acute severe cases, obesity's chronic inflammatory state provides a groundwork for worse outcomes." (PMID 41543809, 2026). "IR itself is associated with obesity, dyslipidemia, hypertension, and increased cardiovascular risk, while elevated inflammatory markers such as CRP and IL-6 reflect a chronic low-grade inflammatory state that may further amplify multiorgan involvement." (PMID 41302170, 2025). "One of the supporting studies is that the inhibition of autophagy using small interfering RNA targeted to Atg7 increases proinflammatory gene expression (i.e., IL-1β, IL-6, and IL-8) in adipose tissue, thus suggesting that autophagy acts to suppress inflammation that is excessive during obesity." (PMID 41194853, 2025). "In patients with obesity, IL-6 levels correlate with inflammation." (PMID 41011232, 2025). "Obesity contributes to tumor progression not only through excess adiposity but also via a chronic inflammatory state characterized by elevated cytokines (e.g., IL-6, TNF-α) and adipokines such as leptin." (PMID 41008885, 2025). "Numerous other cytokines (e.g. IL‐1β, IL‐6, IL‐17) have also been demonstrated to drive lipolysis in cultured adipocytes, which is puzzling, as these cytokines are all elevated during obesity." (PMID 39428707, 2025). "Since obesity is a systemic low-grade inflammation associated with increased plasma levels of inflammatory markers including C-reactive Protein (CRP) and IL-6, the potential role of DHA as an anti-inflammatory agent has to be investigated in children with obesity." (PMID 39186221, 2025). "Also, IL-6 plays a central role in the transition from local inflammation (localized to adipose tissue) to systemic inflammation in obesity, which is marked by raised inflammatory markers in the blood." (PMID 40003433, 2025). "This may be attributed to the increased release of pro-inflammatory factors such as TNF-α and IL-6 in patients with higher levels of obesity, which inhibit nerve regeneration and lead to slower postoperative recovery of neural signal conduction." (PMID 40491428, 2025).
Obesity (continued). "Furthermore, in obesity, adipose-derived cytokines like IL-6, TNFα, and IL-1β activate and recruit macrophages to the liver, promoting liver inflammation, hepatocyte damage, and fibrosis." (PMID 40864559, 2025). "Obesity, a significant risk factor for GD, highlights the role of adipose tissue as an endocrine organ secreting adipokines and pro-inflammatory cytokines like tumor necrosis factor α (TNF-α) and interleukin (IL) IL-6." (PMID 40941639, 2025). "Several others, 8-OHdG, Ca2+, IL-6, IL-8, resistin, TNF-α, and AEA, have been identified as predictors, as they have previously been associated with an increased risk of developing obesity-related conditions such as insulin resistance, metabolic syndrome, or cardiovascular disease." (PMID 40153192, 2025). "Meanwhile, the trans-signaling pathway, which occurs when IL-6 binds to the soluble receptor sIL-6R and activates the gp130 protein in several cells, is related to chronic inflammatory responses, especially in individuals with obesity." (PMID 40647244, 2025). "IL6 and TNFα are found in high levels of obesity and activate the PI3K/Akt pathway." (PMID 40040878, 2025). "The present study aims to investigate the association of GHSR-1a immunopositive (+) cells from atherosclerotic plaque and PVAT with inflammatory markers (tissue concentrations of CRP, Il-6, leptin, and adiponectin) by studying the arteries harvested from patients with obesity and PAD." (PMID 40137085, 2025). "Changes in obesity-related measures have also been correlated with changes in IL-6 and CRP." (PMID 40895542, 2025). "In the obesity and diabetes groups, the levels of pro-inflammatory cytokines such as resistin, leptin, IL-6, and TNF-α were high, which might have expanded the mass of dysfunctional adipose tissue." (PMID 40095937, 2025). "Obesity aggregates tumor development and metastasis in ovarian cancer by upregulating IL-6 expression to boost the recruitment of myeloid-derived suppressor cells (MDSCs), causing overexpression of immune suppression-associated genes and cancer cell immune evasion." (PMID 40863244, 2025). "Interleukin-6 (IL-6) is another key cytokine in obesity-induced low-grade inflammation." (PMID 40218888, 2025). "LPS treatment activates the TLR4/NFκB signaling pathway, leading to the upregulation of pro-inflammatory genes such as IL-6 and VCAM-1, which are key mediators of vascular inflammation and endothelial dysfunction commonly associated with obesity and cardiovascular disease." (PMID 41010478, 2025). "Obesity fosters a state of chronic low-grade inflammation through adipose tissue dysfunction, characterized by the excessive secretion of pro-inflammatory cytokines such as IL-6, TNF-α, and IL-1β." (PMID 40004007, 2025). "In addition to its anti-adipogenic effects, ASA also reduces the obesity-induced expression of inflammatory cytokines (IL-6, TNFα, and MCP-1) and adhesion molecules (ICAM-I and VCAM-I) while enhancing insulin sensitivity in high-fat diet-induced obese mice." (PMID 39859567, 2025). "Increased levels of IL-6 in the serum of patients with both asthma and obesity have been reported." (PMID 40696834, 2025). "Visceral adipose tissue is an active endocrine organ that secretes proinflammatory cytokines such as tumor necrosis factor-alpha (TNF-α), interleukin-6 (IL-6), and C-reactive protein (CRP), which contribute to systemic low-grade inflammation, a hallmark of obesity-related metabolic dysfunction." (PMID 40805992, 2025). "Furthermore, a study in Caucasian adults with obesity and metabolic syndrome showed that energy-restricted diets with plant-based protein reduced inflammatory markers, including IL-6, to a greater extent than diets with animal-based protein." (PMID 41190148, 2025).